JAK2 (Janus kinase 2)
Diseases named in the same sentence as JAK2 in open-access papers (continued):
Sharing a sentence is not in itself a finding about the gene and the disease.
myeloproliferative neoplasm (continued). "Hsp90 is a therapeutic target in JAK2-dependent myeloproliferative neoplasms, RPSA is highly expressed in Acute Myeloid Leukaemia (AML) and SET expression is induced in Chronic Myelogenous Leukemia (CML)." (PMID 22723854, 2012). "A recurrent dominant gain-of-function mutation in JAK2, JAK2V617F, results in constitutional activation of its kinase domain and has been widely established to be causally related to chronic myeloproliferative disorders, particularly polycythemia vera." (PMID 22549126, 2012). "This case report provides additional strong support for a role for JAK2 activation in chronic myeloproliferative disorders." (PMID 22549126, 2012). "Examples include the inhibition of the epidermal growth-factor (EGF)receptors, over-expressed in many solid tumors, and inhibition of Jak2 orBcr-Abl in myeloproliferative disease and leukemia." (PMID 22969412, 2012). "Recently, it has also been demonstrated that JAK2 inhibitors are unable to target uncommitted hematopoietic progenitors responsible of the initiation of the myeloproliferative disease." (PMID 22400031, 2012). "It is expected that, in order to cure the myeloproliferative disease, JAK2 inhibitors should be combined with other drugs to target simultaneously different pathways and to target the initiator hematopoietic cell population in myeloproliferative disorders." (PMID 22400031, 2012). "Although several Jak2 inhibitors have been developed and under clinical evaluation, the therapy of patients with myeloproliferative neoplasms with these agents has thus far shown only modest effects at best." (PMID 22087308, 2011). "The activated Jak2-V617F mutant is present in most cases of BCR/ABL-negative myeloproliferative neoplasms and constitutively activates downstream signals from homodimeric cytokine receptors, such as the erythropoietin receptor (EpoR)." (PMID 22087308, 2011). "Although JAK2 mutations at amino acid 617 and nearby positions account for the majority of patients with various forms of myeloproliferative neoplasms (MPNs), a substantial proportion of MPN patients lack a JAK2 mutation." (PMID 21858098, 2011). "Lestaurtinib is an orally bioavailable multikinase inhibitor that has recently been shown to inhibit JAK2 in myeloproliferative disorders." (PMID 21533094, 2011). "Although a specific STAT5 inhibitor has not yet been developed, lestaurtinib (CEP701), a new JAK2 inhibitor that suppresses JAK2/STAT5 signaling is showing promise in clinical trials for myeloproliferative disorders and pancreatic cancer." (PMID 20585448, 2010). "Deregulation of JAK2 is thought to be associated with hematopoietic disorders and oncogenesis, especially in patients with BCR-ABL-negative myeloproliferative neoplasms (MPNs)." (PMID 19744331, 2009). "The constitutively active JAK2 mutant V617F is found in many patients with myeloproliferative diseases, and constitutively phosphorylated STAT3 is found in many solid tumours and haematopoietic malignancies." (PMID 19455144, 2009). "In the spring of 2005, almost simultaneously, five reports appeared describing a mutation in the gene coding for JAK2 also in this pseudo kinase JH2 domain, in patients with chronic myeloproliferative diseases." (PMID 17032464, 2006). "Previous evidence showed that metformin might be a possible therapeutic option for treating JAK2‐mediated myeloproliferative neoplasms." (PMID 41456173, 2026). "Previous data showed evidence that MTF might also be a possible therapeutic option for treating JAK2‐mediated myeloproliferative neoplasms." (PMID 41456173, 2026). "This case suggests that JAK2 gene testing should be conducted for unexplained thrombocytosis; occult infection must be investigated when myeloproliferative neoplasm patients develop leukocytosis; maintaining therapeutic balance is crucial in the dual crisis of thrombosis and sepsis." (PMID 41560006, 2026).
myeloproliferative neoplasm (continued). "Primary myelofibrosis (PMF) is a clonal myeloproliferative neoplasm (MPN) stemming from hematopoietic stem and progenitor cells (HSPCs), frequently associated with mutations in Janus kinase signal transducer (JAK2), calreticulin (CALR), or thrombopoietin receptor (MPL)." (PMID 41268532, 2025). "To detect gene mutation sites, we combined RPA with the CRISPR/Cas12a-based biosensors to diagnose chromosome-negative myeloproliferative neoplasms (MPNs) in Philadelphia by detecting JAK2 V617F mutations using LFA." (PMID 40558442, 2025). "While JAK2 V617F mutation is well-established in myeloproliferative neoplasms (>95% polycythemia vera), its occurrence in non-hematopoietic malignancies is exceptionally rare." (PMID 41438978, 2025). "JAK inhibitors display very good clinical responses in patients with myeloproliferative neoplasms, irrespective of JAK2 mutational status." (PMID 40413183, 2025). "JAK2 V617 F mutation is a known risk factor for potentially life-threatening vascular complications with or without meeting the criteria of myeloproliferative neoplasm." (PMID 40214958, 2025). "The activated JAK2/STAT pathway is characteristic of myeloproliferative neoplasms (MPNs)." (PMID 40338661, 2025). "Latent myeloproliferative neoplasms are diagnostically challenging clonal hematopoietic disorders characterized by the JAK2 V617F mutation without overt hematologic abnormalities." (PMID 40605890, 2025). "GOF mutations in JAKs (JAK1, JAK2, JAK3) and STATs (particularly STAT3 and STAT5B), as well as alterations in cytokine receptors (IL7R, CRLF2) and negative regulators (SOCS1, PTPN2), are recurrent in myeloproliferative neoplasms and certain lymphoid cancers." (PMID 41438753, 2025). "Essential thrombocythaemia (ET) is one of four chronic myeloproliferative neoplasms (MPN), characterised by clonal thrombocytosis; approximately 85% of patients will have a pathognomonic driver mutation at presentation—JAK-2 (about 50%), CALR (about 30%) or MPL (about 5%)." (PMID 41464542, 2025). "Persistence of JAK2-mutated clones that may undergo clonal evolution and malignant transformation remains a challenge in myeloproliferative neoplasms (MPN), Novel therapeutic approaches to attenuate clonal evolution and progression to blast-phase are therefore urgently needed." (PMID 40781484, 2025). "Genetic testing in this patient was essential to exclude mutations associated with hematologic malignancies, such as JAK2 or CALR mutations, which could explain myeloproliferative neoplasms or other findings." (PMID 40969728, 2025). "CHZ868 is primarily used to treat JAK2 mutant myeloproliferative neoplasms and B-ALL." (PMID 39891728, 2025). "The patient also tested negative for the JAK2 mutation, effectively ruling out an associated myeloproliferative neoplasm, which can occasionally co-occur with ECD." (PMID 41209821, 2025). "Similarly, JAK2 mutations, particularly V617F, are associated with resistance to JAK inhibitors like Ruxolitinib in myeloproliferative neoplasms." (PMID 41144441, 2025). "Fedratinib is a selective JAK2 inhibitor for the treatment of myeloproliferative disease." (PMID 40333091, 2025). "Myelofibrosis (MF) is a rare BCR-ABL negative myeloproliferative neoplasm characterized by clonal proliferation of stem cells, with mutations in JAK2, CALR, or MPL genes." (PMID 38983933, 2024). "Finally, we emphasize PU-H71’s encouraging role in JAK2-dependent myeloproliferative neoplasms, highlighting its potential as a therapeutic avenue in hematology." (PMID 39564119, 2024). "The somatic JAK2 V617F variant has a central role in the pathogenesis of Philadelphia negative (Ph-) myeloproliferative neoplasms (MPN), including essential thrombocythemia, polycythemia vera, and primary myelofibrosis." (PMID 39062663, 2024).
myeloproliferative neoplasm (continued). "Individuals with Philadelphia chromosome-negative myeloproliferative neoplasms (MPNs) such as polycythemia vera and essential thrombocythemia (ET) demonstrate an increased thrombotic risk associated with JAK2 mutations." (PMID 39156349, 2024). "Alternatively, successful treatment may require deeper and more prolonged JAK inhibition, as suggested by genetic modeling of JAK2-driven myeloproliferative neoplasms." (PMID 39510293, 2024). "Additionally, the present report also suggests the promising role of PU-H71 in JAK2-dependent myeloproliferative neoplasms." (PMID 39564119, 2024). "Epigenetic silencing of SOCS1 and SOCS3 genes was observed in patients and murine models of chronic myeloproliferative disorders and AML expressing JAK2(V617F) mutation, suggesting that JAK/STAT contributes to growth factor hypersensitivity induced by JAK2 mutations." (PMID 39308891, 2024). "The JAK2 V617F is a prevalent driver mutation in Philadelphia chromosome-negative myeloproliferative neoplasms (Ph−MPNs), significantly affecting disease progression, immunophenotype, and patient outcomes." (PMID 39043913, 2024). "Myeloproliferative neoplasms (MPN) include chronic myeloid leukemia (CML), the JAK2/MPL/CALR-associated MPN (essential thrombocythemia, primary myelofibrosis, and polycythemia vera), chronic neutrophilic leukemia (CNL), chronic eosinophilic leukemia, and MPN-NOS/unclassifiable." (PMID 39075565, 2024). "Tests for myeloproliferative neoplasm-related genes, such as JAK2 V617F and PDGFRα, were negative, and secondary causes such as parasitic infections, asthma, and allergies were excluded." (PMID 39703993, 2024). "It has been demonstrated previously that human leukocyte antigen class I (HLA-I) and class II (HLA-II) alleles may modulate JAK2 V617F and CALR mutation (CALRmut)-associated oncogenesis in myeloproliferative neoplasms (MPNs)." (PMID 39351227, 2024). "Recently, a JAK2 V617F mutation was also detected in the monocyte endothelial cells of Philadelphia-negative myeloproliferative diseases, adding a novel promoting factor in thrombosis risk." (PMID 38672756, 2024). "The activation of JAK2 in myeloproliferative neoplasms (MPNs) leads to the phosphorylation of the receptors at the cytoplasmic tail, thus creating docking sites for SH2 domain-containing signaling proteins such as the signal transducer and activator of transcription (STAT3 and STAT5)." (PMID 37239426, 2023). "Interestingly, the combination of the JAK2 mutation and chromosome 9p LOH was recognized as a distinct genomic subgroup among myeloproliferative neoplasms." (PMID 37297002, 2023). "Myeloproliferative neoplasms (MPNs) are characterized by the activated JAK2/STAT pathway." (PMID 36719747, 2023). "Differently, rs4495487 SNP is associated with the JAK2-positive myeloproliferative neoplasm in the Japanese population, and the rs10974947 SNP in the JAK2 gene is involved only in polycythemia vera, and not other myeloproliferative disorders." (PMID 37893484, 2023). "Polycythemia vera (PV) is a chronic myeloproliferative neoplasm characterized by erythrocytosis, bone marrow hypercellularity, and activating Janus kinase (JAK) mutations (JAK2V617F or JAK2 exon 12 mutations) that is estimated to affect more than 100,000 people in the USA." (PMID 36944847, 2023). "In addition, the MOLM16 cells contain the JAK2 V617F mutation in the JH2 pseudokinase domain of the JAK2 gene, frequently observed in MDS and myeloproliferative disorders (MPD) and has been linked to leukemogenesis." (PMID 36982453, 2023). "Here, we review the role of JAK2 in myeloproliferative neoplasms." (PMID 35215273, 2022). "The JAK2 p.L611S mutation identified in this case has not been recognized as a driver mutation of myeloproliferative neoplasm." (PMID 35237453, 2022).
myeloproliferative neoplasm (continued). "Curcumin is also able to inhibit the Janus Kinase 2/Signal Transducers and Activators of Transcription (JAK2/STAT) pathways in different types of myeloproliferative neoplasms, a finding that is remarkable given the growing relevance of JAK/STAT-inhibition in the treatment of rheumatic diseases." (PMID 35629033, 2022). "In another case report, the JAK2 mutation was reported to be associated with thromboembolism in a young patient without the myeloproliferative disorder." (PMID 35800822, 2022). "A negative JAK2 mutation hypothetically excluded the presence of an autonomous myeloproliferative disease at the time of detection." (PMID 35453637, 2022). "Furthermore, as clinical data regarding the limitations of approved JAK inhibitors in myeloproliferative disorders matures, there is a growing awareness of the need for alternative precision medicine approaches for specific JAK2 lesions." (PMID 35903543, 2022). "Recently, HDAC11 was shown to be important for the proliferation of oncogenic JAK2-driven myeloproliferative neoplasms, and downregulation of HDAC11 expression could promote apoptosis in human leukaemia." (PMID 34395273, 2021). "Myeloproliferative neoplasms (MPN) show dysregulated JAK2 signaling." (PMID 34480104, 2021). "The process that results in activated platelet-related thrombosis in myeloproliferative neoplasms includes intrinsic platelet abnormalities due to transformed haematopoietic stem cell function that brings about overactive JAK2-dependent signaling and various extrinsic factors." (PMID 34831257, 2021). "Seventy-one patients with BCR-ABL negative myeloproliferative neoplasms were evaluated for JAK2 V617F, CALR type 1, CALR type 2, and MPL by allele-specific PCR and conventional PCR from 2018 to 2019." (PMID 33936230, 2021). "Paradoxically, although the myeloproliferative neoplasms are classified as neoplasms because they are clonal hematopoietic stem cell disorders, the mutations affecting MPL or JAK2 are gain-of-function, resulting in increased production of normal erythrocytes, myeloid cells and platelets." (PMID 33777803, 2021). "Jak2 has a role in several different types of cancers and myeloproliferative diseases." (PMID 34199353, 2021). "Furthermore, one mutation V617F in JAK2 has been identified in one patient with myeloproliferative disorder (MPD) and HCM, suggesting a potential causative role of JAK2 in the development of HCM phenotype." (PMID 34225646, 2021). "JAK2 rs V617F mutation must be considered in any case of PVT with liver cirrhosis and hepatocellular carcinoma without identified thrombophilic risk factors, with potential considerations of evolving myeloproliferative disorders." (PMID 33507708, 2021). "Thus, the present study proposes USP9X inhibitors along with BH3 mimetics as promising agents for novel therapeutic strategies against JAK2-V617F-positive myeloproliferative neoplasms, particularly under the ruxolitinib persistence condition." (PMID 32050632, 2020). "Thus, USP9X represents a promising target along with anti-apoptotic Bcl-2 family members for novel therapeutic strategies against JAK2-V617F-positive myeloproliferative neoplasms, particularly under the ruxolitinib persistence conditions." (PMID 32050632, 2020). "The discovery of a novel JAK2V617F mutation, which is found in 50–90% of all classical MPNs and results in a substitution of valine to phenylalanine in the JAK2 gene, significantly contributed to the discovery of the molecular pathogenesis of myeloproliferative neoplasms." (PMID 32604862, 2020). "MPL W515R was detected in 3/44 cases in low frequencies.Very low allele frequencies of JAK2 and MPL variants in patients with abdominal vein thromboses may indicate early manifestations of myeloproliferative neoplasms." (PMID 33317584, 2020). "JAK2-V617F plays a key role in the pathogenesis of myeloproliferative neoplasm." (PMID 32050632, 2020).
myeloproliferative neoplasm (continued). "It is also interesting to note that 52.4% (95% CI, 38% to 66.5%) of patients with JAK2 mutation did not have a diagnosis of myeloproliferative neoplasm at presentation of SVT but were diagnosed during the follow up." (PMID 32726911, 2020). "However, given the higher prevalence of JAK2 mutation in patients with SVT, JAK2V617F mutation testing to screen for a myeloproliferative disorder should be considered in patients with unprovoked events." (PMID 32726911, 2020). "The Philadelphia chromosome-negative myeloproliferative neoplasms (MPN) share similar molecular characteristics in that they frequently harbor hotspot mutations in JAK2, CALR or MPL, leading to activated JAK/STAT signaling." (PMID 31071164, 2019). "The JAK2-STAT signaling pathway plays a critical role in myeloproliferative neoplasms (MPN)." (PMID 30717771, 2019). "However, primary cultures can still help diagnose patients with myeloproliferative disorders with normal (wild type) Jak-2 gene." (PMID 31810354, 2019). "The JAK2 V617F mutation appears to increase proneness for thrombosis even without overt chronic myeloproliferative disorders." (PMID 31741612, 2019). "Anemia and thrombocytopenia are the most commonly reported hematologic adverse events in studies of the JAK2 inhibitor ruxolitinib in patients with myeloproliferative disorders, but rarely lead to treatment discontinuation and counts often stabilize during treatment." (PMID 31409327, 2019). "This may provide important insights into the structural basis for the inhibition of JAK2, which may aid in the fight against cancer, in particular myeloproliferative neoplasms." (PMID 31805692, 2019). "JAK2 inhibitors are extremely promising therapeutic tools for myeloproliferative neoplasms." (PMID 29867515, 2018). "In contrast, cells that harbor STAT5-activating mutated or modified oncoproteins, like BCR-ABL, JAK2 V617F, mutant MPL (thrombopoietin receptor), and mutant calreticulin in myeloproliferative neoplasms will exhibit persistent activation of STAT5, with high constant levels in the nucleus." (PMID 29728695, 2018). "This might be of particular relevance in the case of JAK2-driven leukemia such as JAK2V617F-induced myeloproliferative neoplasms." (PMID 30671064, 2018). "(2015) with respect to the order of JAK2 and TET2 mutations in myeloproliferative neoplasms." (PMID 29656894, 2018). "Application of a next-generation sequencing (NGS) approach targeted for myeloid malignancies confirmed wild-type JAK2 exons 12–15 and identified a common SH2B3 W262R single-nucleotide polymorphism associated with the development of hematological features of myeloproliferative neoplasms (MPNs)." (PMID 29682367, 2018). "We were not able to collect data on potential predictors of breakthrough PE beyond active cancer diagnosis as testing for antiphospholipid syndrome, established myeloproliferative neoplasm, and JAK2 V617F mutation are not routine in our system." (PMID 29760849, 2018). "Janus kinase 2 (JAK2) mutation was discovered in 2005 in Ph chromosome negative myeloproliferative disorders and was found in the whole of PV cases and about 50% of the ET and PMF cases." (PMID 29732039, 2018). "Most myeloproliferative neoplasm (MPN) patients lacking JAK2 mutations harbour somatic CALR mutations that are thought to activate cytokine signalling although the mechanism is unclear." (PMID 27740635, 2017). "JAK2 activation is the driver mechanism in BCR-ABL-negative myeloproliferative neoplasms (MPN)." (PMID 28903325, 2017). "IL-27R can transform hematopoietic cells through its ability to constitutively activate a mutant form of JAK2, suggesting that it may play unappreciated roles in myeloproliferative neoplasms." (PMID 27119567, 2016). "The simultaneous occurrence of multiple myeloma and JAK2 positive myeloproliferative neoplasms is possible, although the underlying mechanism is not very well understood." (PMID 25914740, 2015).